CCL18 (C-C motif chemokine ligand 18)
Diseases named in the same sentence as CCL18 in open-access papers (continued):
Sharing a sentence is not in itself a finding about the gene and the disease.
peritonitis (3 papers, 2017 to 2023). Inflammation of the peritoneum (tissue that lines the abdominal wall and covers most of the organs in the abdomen). "In conclusion, our study suggests that the chemokine CCL18 can be a mediator of peritoneal membrane failure associated with peritonitis episodes, as well as providing a new potential therapeutic target." (PMID 29850544, 2018). "Given that CCL18 is involved in fibrotic processes and recurrent peritonitis, it is a risk factor for peritoneal membrane failure; thus, we evaluated CCL18 concentrations in peritoneal effluents from patients undergoing peritonitis episodes." (PMID 29850544, 2018). "In conclusion, our study suggests that the chemokine CCL18 can be a mediator of peritoneal membrane failure associated with peritonitis episodes and might provide a new potential therapeutic target." (PMID 29850544, 2018). "The mean concentration of CCL18 in peritonitis samples was 15.02 ± 7.87 ng/ml, whereas mean values previously reported ranged between 1 and 6 ng/ml." (PMID 29850544, 2018). "The differences between a peritoneal inflammatory recognized marker, IL-6, and CCL18 during peritonitis episodes should be remarked." (PMID 29850544, 2018). "The high concentrations during IP are consistent with a previous finding showing that pMΦs from patients undergoing peritonitis or who recently had peritonitis were able to secrete higher amounts of CCL18 compared with pMΦs from uninfected patients." (PMID 29850544, 2018). "CCL18 effluent concentrations showed the highest values during the first days of peritonitis and decreased slowly following a kinetics similar to absolute macrophage counts in these samples and in agreement with previous reports describing macrophages as the primary source of this chemokine." (PMID 29850544, 2018). "Other early events, such as peritonitis or use of high glucose dialysis solutions, were also associated with higher CCL18 values (data not shown)." (PMID 28414753, 2017). "Moreover, CD163+ M2 expressing CCL18 infiltrate the peritoneum in PD patients; their number increases during peritonitis episodes; and peritoneal macrophages isolated from patients with active infectious peritonitis synthesize high amounts of CCL18 when cultured ex vivo." (PMID 29850544, 2018). "Given that high levels of the human chemokine CCL18 have been shown to be related to peritoneal membrane failure and fibrosis, whereas sustained low CCL18 peritoneal concentrations appear to be protective, we evaluated CCL18 levels in the peritoneum of patients undergoing peritonitis episodes." (PMID 29850544, 2018).
phyllodes tumor (3 papers, 2023). A benign, borderline, or malignant fibroepithelial neoplasm arising from the breast and rarely the prostate gland. "Additional research indicates that an established positive feedback mechanism involving CCL5 and CCL18 between M2 macrophages and myofibroblasts contributes to the malignant progression of phyllodes tumors." (PMID 37671155, 2023). "Furthermore, CCL18 induces myofibroblast differentiation and promotes the proliferation and invasion of Phyllodes tumor cells." (PMID 36418470, 2023). "Previous studies also proposed that TAMs could stimulate myofibroblast differentiation and promote proliferation as well as invasion of phyllodes tumors by the CCL18-driven NF-kB/PTEN/AKT axis." (PMID 37240386, 2023).
psoriasis (3 papers, 2016 to 2026). An autoimmune condition characterized by red, well-delineated plaques with silvery scales that are usually on the extensor surfaces and scalp. "The JAK/STAT signaling and spleen tyrosine kinase (SYK) pathways are implicated in numerous autoimmune and inflammatory diseases (e.g. AD, psoriasis, alopecia areata), modulating a range of immune responses, including the Th2 (IL-4, IL-13, CCL18), Th1 (IFNγ), and Th17/Th22 (CCL20, S100As) pathways." (PMID 33329590, 2020).
uveal melanoma (3 papers, 2020 to 2023). A melanoma derived from melanocytes of the uveal tract. "Next, we tested the involvement of chemokines CXC11 and CCL18 as well as VEGFA as they were found involved in uveal melanoma recruitment of tumor-associated microphages and angiogenesis." (PMID 32756477, 2020). "To verify our computational findings, we tested the mRNA expression level of CCL18, CXCL8, GTPBP1, JAG2, PRELID1 and PTGER4 in uveal melanoma cell lines: M17, M23 and SP6.5 and normal uveal epithelial cell: Um95." (PMID 36597071, 2023).
acute myocardial infarction (2 papers, 2019 to 2024). Necrosis of the myocardium, as a result of interruption of the blood supply to the area. "The concentrations of SPP1 and CCL18 have been significantly and consistently upregulated within the local versus peripheral blood of acute myocardial infarction." (PMID 31449494, 2019). "Two subpopulations, with and without an acute myocardial infarction (AMI), identified by a Troponin-T (TnT) cut-off level of 50 ng/L, were studied separately, to assess the influence of an acute TnT response on the prognostic utility of CCL18 in patients admitted to the hospital with suspected ACS." (PMID 38596196, 2024).
allergic disease (2 papers, 2013 to 2021). An immune response that occurs following re-exposure to an innocuous antigen, and that requires the presence of existing antibodies against that antigen. "To evaluate the effects of CCL18 on NK cells in the context of allergy, we compared the chemotactic and cytotoxic response of NK cells from allergic and nonallergic donors." (PMID 33918621, 2021). "CCL18 is a constitutive and inducible chemokine involved in allergic diseases." (PMID 33918621, 2021). "Thus it might be hypothesized that a desensitization phenomenon of the CCL18-receptor occurs due to the increased level of CCL18 in allergic disease." (PMID 23874339, 2013).
Arthritis (2 papers, 2012 to 2021). Inflammation of a joint. "The swollen joint count (SJC) was identified, among which ICAM-1 and CCL18 were reported relevant to synovial tissue in RA, whereas VEGFD was proposed to participate in the pathogenesis of arthritis." (PMID 34869404, 2021).
bacterial pneumonia (2 papers, 2016 to 2025). Acute infection of the lung parenchyma caused by bacteria (e.g., Streptococcus pneumoniae, Haemophilus influenzae, Chlamydia pneumoniae, Mycoplasma pneumoniae, and Legionella pneumophila). "The CCL18, CXCL9, CXCL10, CXCL11, and MMP9 levels were also elevated in patients with other respiratory diseases, such as bacterial pneumonia and COPD." (PMID 40269953, 2025).
bladder tumor (2 papers, 2013 to 2025). "Additional immunohistochemical analysis of bladder tumor tissues confirmed that CCL18 was present only in the inflammatory cells located in the stroma." (PMID 41467176, 2025). "Lastly, immunohistochemical staining for CCL18 and A1AT in human bladder tumors was performed." (PMID 24011266, 2013). "The number of CCL18-positive inflammatory cells per high power field was not increased in bladder tumors compared to controls (1.0 ± 1.2 vs. 4.5 ± 6.9, p = 0.57)." (PMID 24011266, 2013).
crescentic glomerulonephritis (2 papers, 2017 to 2021). A histopathologic term for a pattern of diseases characterized by extensive crescent formation in the glomeruli; patients present clinically with rapid deterioration of renal function, and possible progression to end-stage renal failure within weeks or months. "In accordance to these data, we found that CD163+/CCL18 expressing macrophages colocalized with Gremlin protein expression in another cohort of patients with ANCA-associated crescentic glomerulonephritis." (PMID 34307414, 2021). "A microarray analysis of renal biopsy samples of patients with newly diagnosed ANCA-associated crescentic glomerulonephritis identified CCL18 as the most upregulated gene." (PMID 34307414, 2021).
esophageal cancer (2 papers, 2023 to 2025). A primary or metastatic malignant neoplasm involving the esophagus. "Consistent with the results from the clinicopathological analysis, CCL18 could promote the esophageal cancer cell proliferation." (PMID 36850011, 2023). "Therefore, CCL18 secreted by macrophages in the tumor tissues of ESCC could promote the proliferation of esophageal cancer cells and led the polarization of macrophages toward M2 phenotype." (PMID 36850011, 2023). "Similarly, we discovered that CCL18 could promote proliferation of esophageal cancer cells via its interaction with PITPNM3." (PMID 36850011, 2023). "The esophageal cancer cell line EC-109, which expressed PITPNM3 but not CCL18, was selected in the subsequent in vitro experiment." (PMID 36850011, 2023).
Hyperglycemia (2 papers, 2017 to 2018). An increased concentration of glucose in the blood. "Meanwhile, the expression of CCL18 was suppressed in M2 macrophages by hyperglycemia." (PMID 29081777, 2017). "In primary human monocyte-derived macrophages, hyperglycemia induces the production of the prototype M1 cytokines tumor necrosis factor-α (TNF-α), interleukin-1β (IL-1β), and IL-6, but inhibits the M2 cytokines IL-1Ra and C-C motif chemokine ligand 18 (CCL18) during macrophage differentiation." (PMID 29850615, 2018).
intrahepatic cholangiocarcinoma (2 papers, 2024). A carcinoma that arises from the intrahepatic bile duct epithelium in any site of the intrahepatic biliary tree. "This decrease in CCL18 secretion results in the suppression of malignant behaviors in intrahepatic cholangiocarcinoma (ICC) cells, suggesting a promising therapeutic avenue." (PMID 39286635, 2024). "Moreover, the inhibition of CCL18-mediated STAT3 phosphorylation, through immune responsive gene 1 (IRG1) overexpression, can inhibit macrophages M2-like polarization and impair the progression of intrahepatic cholangiocarcinoma (ICC)." (PMID 38542388, 2024).
ischemia (2 papers, 2012 to 2019). A hypoperfusion of the BLOOD through an organ or tissue caused by a PATHOLOGIC CONSTRICTION or obstruction of its BLOOD VESSELS, or an absence of BLOOD CIRCULATION. "CCL18/PARC has specific chemotactic activity on T cells and this chemokine can activate fibroblasts, thereby directly contributing to lung fibrosis and possibly myocardial fibrosis upon ischemia." (PMID 23029252, 2012). "In contrast, anti-inflammatory activation in patients with ischemia and foot ulcers was characterized by less marked stimulated (but not basal) secretion of CCL18, and an abrupt decrease in both the basal and stimulated cytokines in patients with unrestricted blood flow." (PMID 31877847, 2019). "In conclusion, the analysis of results demonstrates a clear increase in TNF-α and a decrease in CCL18 secretion by blood-derived monocytes from T2DM patients with diabetic foot syndrome in relation to carbohydrate metabolism status (compensated/decompensated) and the severity of ischemia." (PMID 31877847, 2019). "When evaluating ABI values in patients with long-term T2DM without foot ulcers we noted a significant increase in basal and stimulated TNF-α/CCL18 levels in all patients with chronic lower limb ischemia (ABI < 0.8) compared with patients without ischemia (ABI 0.9–1.2)." (PMID 31877847, 2019). "However, we observed insignificant secretion of TNF-α and increased CCL18 in patients with foot ulcers and ischemia, while the basal (not stimulated) level of CCL18 was significantly higher in patients with foot ulcers (p < 0.027) compared to patients without foot ulcers." (PMID 31877847, 2019).
laryngeal squamous cell carcinoma (2 papers, 2019 to 2020). A squamous cell carcinoma that arises from the larynx. "However, the clinical significance of serum CCL18 in patients with laryngeal squamous cell carcinoma (LSCC) remains unknown." (PMID 31839826, 2019).
lepromatous leprosy (2 papers, 2014 to 2015). A chronic communicable infection which is a principal or polar form of leprosy. "Increased CCL18 levels were associated with lepromatous leprosy in randomly generated discovery and validation cohorts in 40/40 (100%) of the iterations, while increased CCL17 levels were associated with tuberculoid lesions in 29/40 (73%)." (PMID 25412496, 2014). "Together, these data suggest that both CCL17 and CCL18 dermal mRNA levels are associated with tuberculoid and lepromatous leprosy, respectively and are more strongly associated with polarity than common TH1/TH2 markers typically used to characterize leprosy lesions." (PMID 25412496, 2014). "As a second biomarker for RR in multiple ethnic backgrounds, increased serum IP-10 levels were identified, whereas CCL18, which is elevated in lepromatous leprosy, decreased at early RR in 6/10 patients who developed RR." (PMID 26510990, 2015). "The dynamics of CCL18 (chemokine (C-C motif) ligand 18) serum levels, elevated in lepromatous leprosy, were also investigated for patients experiencing reactions, showing a decreasing trend at RR, increasing after treatment for most patients." (PMID 26510990, 2015). "Whether or not CCL18 has primary effects on lepromatous leprosy development and persistence is currently unknown." (PMID 25412496, 2014). "Patients with lepromatous leprosy had a non-significant trend (p = 0.16) of decreasing CCL17 levels and a significant trend (p = 0.036) of increasing CCL18 levels in the serum." (PMID 25412496, 2014).
metastatic tumors (2 papers, 2023 to 2024). "A previous study observed a dramatic increase in SPP1+ and MRC1+ CCL18+ macrophages in metastatic tumors, which corroborated the potentially suppressive TME in liver metastases." (PMID 37256123, 2023).
multiple myeloma (2 papers, 2023 to 2024). "Like CCL18/PARC, elevation of TRAP activity also appears in other diseases (Niemann–Pick disease, osteopetrosis, and multiple myeloma, among others)." (PMID 37833892, 2023).
nasal polyp (2 papers, 2016 to 2018). "CCL18 plays a vital role in Th2 inflammation and is mainly produced by M2 macrophage in nasal polyps in Caucasian CRSwNP patients." (PMID 27216292, 2016).
nasopharyngeal carcinoma (2 papers, 2018 to 2025). A carcinoma arising from the nasopharyngeal epithelium. "Nasopharyngeal carcinoma (NPC) cells secrete IFN-stimulated gene 15 (ISG15), which remodels macrophages into the M2 subtype by activating the LFA-1/SFK/CCL18 axis." (PMID 40607254, 2025).
Niemann-Pick disease type B (2 papers, 2017 to 2023). "Nonetheless, the combined analysis of both ChT and CCL18/PARC levels allowed the identification of four additional patients with lysosomal storage diseases: three patients with Niemann-Pick disease type B and one with GD." (PMID 28222799, 2017).
osteonecrosis (2 papers, 2017 to 2024). A none disease characterized by death of bone tissue due to a lack of blood supply. "CCL18 level correlates with liver and spleen volume, platelet count, history of osteonecrosis, and number of anatomical sites of osteonecrosis." (PMID 28427477, 2017).
pneumonia (2 papers, 2018 to 2019). An acute, acute and chronic, or chronic inflammation focally or diffusely affecting the lung parenchyma, caused by an infection in one or both of the lungs (by bacteria, viruses, fungi, or mycoplasma.). "SP-D, YKL-40 and CCL18 levels were higher in patients with severe pneumonia and YKL-40 and CCL18 levels were lower in CAP caused by intracellular, atypical bacteria compared to levels in CAP with other aetiology." (PMID 29324810, 2018). "Predictive value of YKL-40 and CCL18 for pneumonia caused by intracellular bacteria using univariate and multivariate logistic regression analysis." (PMID 29324810, 2018).
preeclampsia (2 papers, 2008 to 2023). Preeclampsia is a hypertensive disorder of pregnancy that is characterized by new-onset hypertension with proteinuria presenting after 20 weeks of gestation, and depending on mild or severe forms may initially present with severe headache, visual disturbances, and hyperreflexia. "Contemporary research recognizes CCL18 as an immune‐related sensitive predictor for preeclampsia." (PMID 37700485, 2023). "Indeed, a number of genes regulated in this array were previously found to be associated with pregnancy complications such as preeclampsia (MR, CCL2, IGF-1, secreted phosphoprotein (SPP)-1, MMP-9), preterm labour (CCL18) and intrauterine growth restriction (IGF-1)." (PMID 18446208, 2008).
Pruritus (2 papers, 2021 to 2022). Pruritus is an itch or a sensation that makes a person want to scratch. "Once more, high blood levels of IL-31 were linked to pruritus intensity and serum and tissue expression of the chemokine CCL18." (PMID 34118946, 2021). "The aim of the study was to analyse serum concentrations of CCL2/MCP-1, CCL3/MIP-1α, CCL4/MIP-1β, CCL5/RANTES, CCL17/TARC, CCL18/PARC, CCL22/MDC and CXCL8/IL-8, and their correlation with PsO severity and pruritus intensity." (PMID 36362116, 2022).
sarcoma (2 papers, 2023 to 2024). A usually aggressive malignant neoplasm of the soft tissue or bone. "While sarcomas exhibit the tumor-promoting effects of CCL18 and IL-6, the impact of other cytokines remains unclear." (PMID 38302407, 2024).
thymoma (2 papers, 2022). A neoplasm arising from the epithelial cells of the thymus. "Consistent with the TCGA thymoma dataset, a significantly higher proportion of patients with WHO type C or Masaoka stage III-IV thymoma had increased expression of CD68 and CCL18." (PMID 35675033, 2022).
triple-negative breast carcinoma (2 papers, 2023 to 2025). An invasive breast carcinoma which is negative for expression of estrogen receptor (ER), progesterone receptor (PR), and human epidermal growth factor receptor 2 (HER2). "To further explore subtype-specific expression patterns, we assessed the expression of CCL18 and EGF across defined molecular subtypes of BRCA, including luminal A, luminal B, HER2-enriched, and triple-negative breast cancer (TNBC)." (PMID 40692603, 2025).
unstable angina (2 papers, 2019 to 2024). "CX3CR1, (CCL5/RANTES) and CC chemokine ligand-18 (CCL18/ PARC) are closely related to refractory unstable angina and can be used as a specific marker, while CX3CL1 is used as a marker of response to statin therapy." (PMID 31934638, 2019). "For total mortality at 7 years follow-up in the non-AMI subset of patients, the area under the ROC curves for loge-transformed AUC values of CCL18 stratified for index diagnosis was 0.59 for unstable angina and 0.66 for non-ACS, respectively." (PMID 38596196, 2024). "As judged by the area under the ROC curve, CCL18 in this subgroup added significant prognostic information beyond that of the index diagnosis, especially in subjects not presenting with unstable angina." (PMID 38596196, 2024).
unstable angina pectoris (2 papers, 2012 to 2019). "For example, the chemokine CCL18 serves as a marker of anti-inflammatory activation and has been validated as a specific marker of refractory unstable angina pectoris." (PMID 31449494, 2019). "Recently, we reported elevated serum levels of CCL5/RANTES and CCL18/PARC in a small patient cohort consisting of subjects with unstable angina pectoris and both chemokines were identified as markers of refractory UAP." (PMID 23029252, 2012).
allergic asthma (1 paper, 2015). A asthma with a basis in a pathological type I hypersensitivity reaction. "For CCL18, it is a differentially coexpressed gene (DCG) in Allergic asthma." (PMID 26450611, 2015).
angiosarcoma (1 paper, 2013). A malignant tumor arising from the endothelial cells of the blood vessels. "The decreased levels of CCL18 from M2 macrophages might correlate with the therapeutic effects of DTX with RS in patients with angiosarcoma." (PMID 24489574, 2013).
Ascites (1 paper, 2016). Accumulation of fluid in the peritoneal cavity (between the layers of the peritoneum that lines the abdomen). "Here, we show that CCL18 levels are markedly increased in advanced serous OC ascites relative to peritoneal effusions from women with benign conditions." (PMID 27613122, 2016). "Women were separated in CCL18 high and low groups based on the CCL18 median level in ascites." (PMID 27613122, 2016).